TNF (tumor necrosis factor)
Diseases named in the same sentence as TNF in open-access papers (continued):
Sharing a sentence is not in itself a finding about the gene and the disease.
infection (continued). "Along with our data indicating that LDHB deficiency does not completely ablate pDC IFN-I production or change TNFα production capacity these data reinforce the idea that multiple mechanisms are likely at play in the enforcement of pDC loss of function after infection." (PMID 39920132, 2025). "Once activated, these cells secrete proinflammatory cytokines, including TNF-α, IL-6, IL-1β, and IL-12 in proportions that vary according to fungal morphology, promoting an environment that favors the differentiation of Th1 and Th17 lymphocytes in the early stages of infection." (PMID 41590416, 2025). "Notably, IL-6 blockade with tocilizumab may offer a relatively safer infection profile compared with TNF or JAK inhibitors." (PMID 41439945, 2025). "Similarly, when examining the modulation of the signalling pathway downstream of TNF, we also measured an increased phosphorylation of IκBα and the subsequent NF-κB translocation in Ubi_K48R cells even at a steady state preceding infection with MNoV_S99 but also subsequent to infection." (PMID 40395509, 2025). "Macrophages migrate to the infection site via chemotaxis, where they recognize and phagocytize fungal pathogens while producing various pro-inflammatory cytokines and chemokines, including TNFα, CXCL1, CXCL2, CCL2, and IL-1β, thereby promoting inflammation and immune defense." (PMID 41190069, 2025). "Notably, mice neutrophils and macrophages secreted much higher amounts of TNF-α in response to infection with Porphyromonas gingivalis than human neutrophils as indicated by the 10-fold higher concentration of the cytokine accumulated in the conditioned medium at 24 h." (PMID 39936030, 2025). "In infections with “atypical” pathogens, such as C. trachomatis, an important role is played by the activation of the immune response with the production of cytokines, including interleukin-1 (IL-1), interleukin-6 (IL-6) and tumor necrosis factor-alpha (TNF-α)." (PMID 40647668, 2025). "However, based on adverse effects like enhanced susceptibility to infection by long‐term inhibition, neither TNF‐α nor NF‐κB are suitable pharmacological targets to decrease inflammaging." (PMID 39434463, 2025). "Infection with the highly contagious SARS-CoV-2 virus, the causative agent behind the coronavirus 2019 (COVID-19) pandemic, has been associated with an increase in circulating tumour-necrosis factor (TNF) and IL-6, in part contributing to hypercoagulation and platelet dysfunction." (PMID 40497942, 2025). "Patients with chronic HCV had decreased trabecular volumetric BMD and cortical dimensions and higher TNF-α than individuals without infection, suggesting that HCV-associated inflammation might contribute to bone deficits." (PMID 40302727, 2025). "Therefore, we hypothesised that BEV may also develop strategies to interfere with TNF-α-induced NF-κB activation during the later stages of infection to evade host immune surveillance." (PMID 39956903, 2025). "Furthermore, HBOT inhibits the production of pro-inflammatory factors, including interferon-γ, prostaglandins, tumor necrosis factor-α, and interleukin-6, while promoting neutrophil apoptosis at the site of infection, thereby facilitating the resolution of inflammation." (PMID 40538733, 2025). "In a mouse infection model, the carmofur treatment group showed a reduction of approximately two log levels in bacterial load in lung tissue and blood, a significant decrease in the levels of inflammatory cytokines TNF-α and IL-6, and an improvement in survival rate to 60%." (PMID 40149043, 2025). "Infection with HTLV-1A/CoI-L resulted in low overall frequency of monocytes, DCs, and neutrophils producing IL-10, with elevated frequencies of those producing TNF-α in both compartments, linked to high expression of IL-6, CCL2, and IL-33 in blood and of MMP1, IL-1β, CCL3, and CCL19 in the lung." (PMID 41006234, 2025).
infection (continued). "Therefore, among elderly individuals who are at a higher risk of infection or have recently undergone cancer treatment, UST may be a more favorable option compared to anti-TNF therapy." (PMID 38455044, 2024). "Wnt signaling molecules, genes associated with inflammation and infection, such as EBF1, TIMP2, COL4A3, TNF, and the candidate gene for schizophrenia, i.e., ABCA13, have been identified as PTB biomarkers through the multiple target studies, though their mechanisms remain unclear." (PMID 38391647, 2024). "However, in the case of immune challenges, such as pathogen infection, where TNF is produced in substantial quantity for a long-term period, both adapters might be required to limit TNF-induced cell death and tissue damage." (PMID 39562788, 2024). "Moreover, hISM1-infection decreased IL-6 and TNF-α levels in aging hearts." (PMID 38300636, 2024). "During mouse infection of B. anthracis or other bacteria, the amount of the pro-inflammatory cytokine TNF in the bloodstream increases to an average level of 200–1000 pg/mL, which is comparable with the serum TNF concentration in the TNF + LT model described in this work." (PMID 37855658, 2024). "Importantly, non-anti-TNF-based therapies are better known to spare vaccine immunogenicity historically and are less linked to increased susceptibility to infection." (PMID 39591183, 2024). "Moreover, a study investigating human metapneumovirus infection in children, it was found that assessing the severity and prognosis of infection may be facilitated by examining IL-6 and TNF-α expression levels." (PMID 38789583, 2024). "Furthermore, gene expression of TNF-α, IL-1β, IL-6, and IL-8 were also significantly upregulated 1 to 5 h after infection by K. pneumoniae, although SeMet reduced inflammation and protein expression of TLR4, Ikappa-B, NF-κB, and TNF-α in bMECs and macrophages infected with ESBL E. coli." (PMID 39456758, 2024). "A series of Mann-Whitney U tests were conducted to determine whether there is a difference in IgG and IgA levels between pARD who were receiving methotrexate (MTX) or TNF-α inhibitors at the time of infection, vaccination, or the second event (Subgroup 3) and those who were not." (PMID 39054538, 2024). "An experimental animal infection study undertaken in Rhesus macaques to determine the mechanisms underlying the inflammation and thrombosis seen in SARS-CoV-2 infection, showed activation of IFN-α, IFN-γ, interleukins, and TNF-α in bronchoalveolar samples on the first day of infection." (PMID 40008234, 2024). "Post-infection, dietary Glut and 1% omega-3 increased intestinal interleukin-10 (IL) and secretory immunoglobulin-A and serum lysozyme, while decreased the elevated inflammatory mediators comprising interleukin IL-6, tumor necrosis factor-alpha, nitric oxide (NO) and inducible NO synthase." (PMID 38961536, 2024). "Moreover, by the 7th day post-infection, the mortality rate of the mice reached 50.0%, indicating complex immune regulatory mechanisms, including overexpression of IL-10 and increased production of pro-inflammatory cytokines like TNF-α." (PMID 39129003, 2024). "Thirteen of the tested proteins (G-CSF, GM-CSF, M-CSF, TNF-β, IFN-gamma, TNF-α, IL-1 β, IL-3, IL-6, IL-7, IL-15, IL-17, IL-19) were found in the hemolymph and hemocytes of G. mellonella; however, the results regarding the influence of infection differed according to the detection method." (PMID 38774871, 2024). "TNF is essential for the formation and maintenance of granulomas, which are organized structures of immune cells that form around the bacteria to contain the infection, though they may also provide a niche where the bacteria can persist in a dormant state." (PMID 38892443, 2024).
infection (continued). "Interestingly, the stimulation of pancreatic islets with very high concentrations of TNF, IFNγ and IL-1β inhibited insulin secretion, indicating that during severe, life-threatening infection these cytokines are involved in facilitating stress-induced hyperglycemia." (PMID 39107476, 2024). "S10 effectively inhibited the secretions of IL-1β and TNF-α in an in vitro inflammatory model of infection induced by P. gingivalis and demonstrates that S10 effectively suppresses the P. gingivalis infection-induced secretions of the pro-inflammatory cytokines IL-1β and TNF-α by THP-1 macrophages." (PMID 38921772, 2024). "Thus, IFNγ may trigger TNF production by astrocytes, which may self-sustain the inflammatory milieu, amplifying the Ser/5-HT-promoted infection of astrocytes by T. cruzi." (PMID 38776344, 2024). "In addition, OROV infection triggered the release of the pro-inflammatory cytokine TNF-α (tumor necrosis factor-α) and led to a decrease in cell viability within 48 hours of infection, suggesting that OROV is capable of inducing an inflammatory response and tissue damage." (PMID 39444684, 2024). "Importantly, PBMC-mtDNA levels were an excellent biomarker to assess cART toxicity since it was correlated with clinical parameters associated with infection (viral load), metabolic alterations (total cholesterol, LDL, ALP, creatin kinase), and inflammation (TNFα)." (PMID 39125986, 2024). "This study showed that B5 could not kill K. pneumoniae in vitro; however, intranasal B5 promoted the recruitment of macrophages and dendritic cells in the lungs in the early infection phase, and inhibited the secretion of TNF-α, IL-1β, and IL-17 in the lungs in the later infection phase." (PMID 39408834, 2024). "In the current study, we found that B5 promoted the mRNA expression of TNF-α and IL-1β in the early infection phase, but inhibited the secretion of TNF-α, IL-1β, and IL-17 in the later infection phase, suggesting that B5 could regulate inflammatory response induced by K. pneumoniae." (PMID 39408834, 2024). "The P0 infection group was enriched mainly in signaling pathways such as the immune response to the virus, while P10 and P240 were enriched mainly in important cell signaling pathways such as the TNF, Toll-like receptor, NOD-like receptor, RIG-I-like receptor, and P13K-Akt pathways." (PMID 39012141, 2024). "Together, both studies favor the assumption that ADAM17 takes a role during infection by modulating the production of inflammatory molecules, mainly TNF, which is required for protective immunity during LTB but could be detrimental when it is produced in excess, as in septic shock." (PMID 38881671, 2024). "After poly(I:C) infection, there was a downregulation of Uchl1 expression, while the expression of Tlr3, Caspase3, Caspase12, NOD-like receptor thermal protein domain associated protein 3 (Nlrp3), Interleukin-1β (IL-1β), IL-6, and Tumor necrosis factor alpha (Tnfα) was significantly upregulated." (PMID 38300431, 2024). "However, the TNFα cytokine levels only increased in the DSS group 2 weeks post-infection." (PMID 38542396, 2024). "Previous reports have indicated TNF inhibitors do not differ in infection risk." (PMID 39070789, 2024). "Generally, infection, tissue damage, or exposure to endotoxins could cause activated M1 macrophages following the production of various pro-inflammatory mediators, such as inducible nitric oxide synthase iNOS, NO, COX-2, TNF-α, IL-1β, and IL-6." (PMID 38393066, 2024). "The TNF-α concentrations detected in our study were generally higher than seen in pigs with mild clinical disease after infection with the Eystrup strain (J. Nielsen, unpublished results) but considerably lower than after infection with the highly virulent Koslov strain." (PMID 38393074, 2024).
infection (continued). "Albumin content in brain homogenates was equivalent between TNF KO and WT mice throughout the course of craniotomy infection, indicating that differences in BBB permeability were not responsible for the transient reductions in leukocyte recruitment observed in TNF-deficient animals." (PMID 39044282, 2024). "In addition, the mRNA expression levels of proinflammatory cytokines downstream of the RIG-I/MDA5 pathway, including IL-6, IL-8 and TNF-α, were also significantly upregulated in the infection group than that in the control group at 12 hpi, 24 hpi and 48 hpi, respectively." (PMID 39502173, 2024). "Growing evidence indicates that CRP plays a significant role in inflammation and the host response to infection, including the complement pathway, apoptosis, phagocytosis, nitric oxide release, and the release of inflammatory cytokines, particularly interleukin-6 and tumor necrosis factor-alpha." (PMID 39610974, 2024). "Despite these changes, infection was not worsened by TNF loss at any time point examined, which may result from S. aureus-derived factors unique to biofilm growth." (PMID 39044282, 2024). "In contrast, at the TNFα promoter, there was a trend towards increased methylation post- compared to pre-infection (p = 0.0942); however, this increase was only observed in 3 of 4 animals while the levels decreased in 1 of 4 animals post- compared with pre-infection." (PMID 39772149, 2024). "Due to the change in the ROS and RNS production during BMDMs infection with Mtb and RvΔ0687, we further hypothesized this could impact the secretion of cytokines or chemokines and analyzed the levels of IL-1β, TNF-α, MIP-1α and IP-10 cytokines in the supernatants of BMDMs infected with Mtb strains." (PMID 39063103, 2024). "Moreover, infection with S. aureus reportedly elevates IL-22–derived γδ T cells in mechanically injured skin, and these cells have been identified as protective against S. aureus reinfection by producing TNF-α and IFN-γ via the TLR2/MyD88 signaling pathway." (PMID 38319737, 2024). "Besides, TNF-α increases the IFN-γ response against infection." (PMID 39213335, 2024). "Moreover, the wound dehydration and infection could also stimulate the proinflammatory cytokines production (e.g., IL-1 and TNF-α) with stalled inflammation phase leading to scar formation." (PMID 39141725, 2024). "The disruption of the epithelial barrier due to intestinal dysbiosis, infection, and injury results in the entry of bacteria and their metabolites into the bloodstream, which can promote systemic inflammation characterized by elevated plasma TNF-α, IL-6, and IL-1β levels." (PMID 36675302, 2023). "Our findings also confirmed that T. gondii Wh6 infection upregulated the expression of IL-6, TNF-α and IL-1β in the PFC region, which was restricted by β-glucan, suggesting that the neuroinflammation and cytotoxicity of hyperactivated glial cells could be reduced by β-glucan." (PMID 36782332, 2023). "We conclude that virus binding gives rise to a limited IL-6 and TNFα transitory release and that both the presence of the viral DNA within infectious particles and latent gene expression are required to reach maximal cytokine transcription and release, a process that started 2 hours post-infection." (PMID 37830871, 2023). "Furthermore, IL-1β and TNF-α can express acute inflammation, infection, and cancer." (PMID 37513454, 2023). "At the beginning of the infection, classically activated macrophages (or M1) are activated to phagocytize and clear the invading pathogens, creating a pro-inflammatory microenvironment dominated by Th-1 cytokines, such as INF-γ and TNF-α cytokines, which also causes tissue injury as a consequence." (PMID 36668953, 2023). "Interestingly, the infection of cells with Y. pseudotuberculosis inhibits TNF production, but apoptosis can still be induced by TNF produced by additional effector cells recruited to the site of infection or by surface TNF." (PMID 38112844, 2023).
infection (continued). "It revealed that infection of F. necrophorum can induce an inflammatory response in the intertoe skin explants, leading to the activation of the inflammatory pathway of NF-κB, and an up-regulation of the expression of inflammatory cytokines TNF-α, IL-8, and IL-1β." (PMID 37153149, 2023). "However, we observed a host species-specific difference in TNFα mRNA levels during infection." (PMID 36793725, 2023). "Whether anti-TNF therapies increase the risk of infections is not definitive, though newer biologics, including vedolizumab and ustekinumab, are thought to be safer with lower risk of adverse events." (PMID 37674503, 2023). "While it is clear that TNF signaling is required for protection of macrophages against pathogens like L. pneumophila, the mechanisms by which this signaling protects cells from infection remain unclear." (PMID 37279255, 2023). "In addition, infection with S17 was associated with a reduced inflammatory response, including reduced bronchoalveolar lavage fluid (BAL) polymorphonuclear (PMN) cell count, and reduced BAL TNF, IL-1β, and IL-12p40 levels." (PMID 37056705, 2023). "Hence high expression of TNF-α and low expression of IL-10 may result in the low infection rates in this patient population." (PMID 37428723, 2023). "Delta and Omicron infection only marginally altered mRNA expression of IL-1β (Delta vs Mock: p = 0.6114; Omicron vs Mock: p = 0.7534), IL-6 (p = 0.1910; p = 0.2619), IL-18 (p = 0.7755; p = 0.6092), TNF-α (p = 0.9080; p = 0.9405) and IFN-α (p = 0.0612; p = 0.2138)." (PMID 36883057, 2023). "The broad range of TNFα, IL-6, and IFNα responses seen among the IAV patients suggest that seasonal IAV strains are associated with milder cytokine responses than those observed during infections with 2009 H1N1 pandemic influenza or highly pathogenic avian H5N1 strains." (PMID 36752598, 2023). "Moreover, type 1 cytokines (TNF-α and IFN-γ) change their protective nature to promote the spread of disease and use their distinct association with bacterial density to indicate the severity of an infection." (PMID 38481606, 2023). "Additionally, in contrast to anti-viral agents that require early intervention, we show that neutralization of IFN-γ and TNF, or IL-1β activity in the aftermath of infection can serve as “pro-repair strategies” to augment alveolar regeneration and dampen fibrotic sequelae." (PMID 38077031, 2023). "Hence, we attempted to explore whether the Del2R infection enhances IL-1β and TNF-α production in vivo." (PMID 37566637, 2023). "In vitro studies suggest that IFNγ fuels astrocyte infection by T. cruzi and implicate IFNγ-stimulated infected astrocytes as sources of TNF and nitric oxide, which may also contribute to parasite persistence in the brain tissue and promote behavioural and neurocognitive changes." (PMID 37018799, 2023). "Transcripts encoding the inflammatory cytokines, TNF-α, IL-1β and IL-6, were not consistently detected in monolayers subjected to mock infection with medium alone, but infection with all of the DENV isolates stimulated IL-6 expression, although notably higher levels were seen with DENV2 strains." (PMID 37515098, 2023). "Next, we used enzyme-linked immunosorbent assay (ELISA) to investigate whether SaaS mediated the secretion of cytokines in vivo, with the interleukin-1β (IL-1β), IL-8, and tumor necrosis factor alpha (TNF-α) levels in serum after infection being examined with ELISA." (PMID 36688642, 2023). "In addition, sickness behaviors from this infection are inhibited by TNF neutralization." (PMID 38115011, 2023). "However, the immune response in the liver at late stages of the primary infection exerted a mixed Th1/Th2 response including the participation of cytokines such as IL-1β, TNF-α, TGF-β and IL-4 as it has been reported during acute and chronic stages in ruminants and other species." (PMID 36627694, 2023).